IL32 (interleukin 32)
Diseases named in the same sentence as IL32 in open-access papers (continued):
Sharing a sentence is not in itself a finding about the gene and the disease.
lymph node metastasis (6 papers, 2015 to 2024). "The increase in IL32 expression is associated with tumor staging, lymph node metastasis, and distant metastasis in PRAD, KIRC, PAAD, and THCA." (PMID 38584169, 2024). "In ESCC, advanced stage and lymph node metastasis were associated with significant IL-32 upregulation." (PMID 33020452, 2020). "Others have shown higher rates of IL32-immunopositivity in primary tumors derived from patients with lymph node metastasis as well as in metastatic as compared to corresponding primary tumors, regardless the location of distant metastases." (PMID 33020452, 2020). "Interestingly, higher IL-32 was detected in the advanced stages of lymph node metastasis (P < 0.05)." (PMID 35428295, 2022). "Over-expression of IL-32 may stimulate the organic metastasis and the lymph node metastasis of CRC." (PMID 25889282, 2015). "Thus, IL-32 expression may stimulate the organic metastasis and the lymph node metastasis of CRC." (PMID 25889282, 2015). "The positive rate of IL-32 in primary CRC with lymph node metastasis was more severe than that of IL-32 in primary CRC without lymph node metastasis (P < 0.05)." (PMID 25889282, 2015). "Here, IHC IL-32 expression pattern of primary lesions with no lymph node metastasis was compared with primary lesions with lymph node metastasis." (PMID 25889282, 2015). "The result showed that the rate of IL-32-positive cases of CRC lymph node metastases was 60%, much higher than those without lymph node metastasis." (PMID 25889282, 2015).
osteoarthritis (6 papers, 2013 to 2025). A noninflammatory degenerative joint disease occurring chiefly in older persons, characterized by degeneration of the articular cartilage, hypertrophy of bone at the margins and changes in the synovial membrane. "In contrast, fewer CD8+ T cells producing CXCL14 and IL-32 were identified in osteoarthritis synovium." (PMID 39114979, 2024). "In the case of RA and compared to both healthy controls and patients with osteoarthritis, IL-32 expression was higher in RA patients; moreover, the synovial biopsies of RA patients exhibit a reduction of IL-32 upon anti-TNFα treatment." (PMID 35281066, 2022). "Increased levels of IL-32γ in synovial biopsies and IL-32 in synovial fibroblasts have been demonstrated in RA patients compared to those with osteoarthritis, suggesting that the modulation of IL-32 isoforms could be a strategy for controlling inflammation." (PMID 40299461, 2025). "To demonstrate the clinical relevance of CXCL14- and IL-32–producing cells in PsA, we stained synovial tissue sections collected from patients with PsA and osteoarthritis and found IL-32+ and CXCL14+ cells in the synovial lining area and ectopic lymphoid aggregates of the patient with PsA." (PMID 39114979, 2024).
prostate carcinoma (6 papers, 2013 to 2021). A carcinoma that arises from epithelial cells of the prostate gland. "MiR-205 is down-regulated in prostate cancer, and its restoration reduces cell proliferation by activating the interleukin 24 and interleukin 32 (IL24 and IL32) genes." (PMID 29401683, 2018). "Moreover, in prostate cancer, miR-205 also upregulated the tumour suppressor genes IL-24 and IL-32 mRNA and protein by targeting their promoters." (PMID 33109127, 2020). "Additionally, miR-205 positively regulates transcriptional activation of the tumour-suppressor genes interleukin (IL)-24 and IL-32 in prostate cancer and directly regulates IL-24 in human KB oral cancer cells." (PMID 33109127, 2020). "MiR-205 increases the expression of tumor suppressor genes IL24 and IL32 in prostate cancer." (PMID 29471827, 2018). "In prostate carcinoma cells, miR-205 activates IL-24 and IL-32 by targeting their promoters." (PMID 29471827, 2018). "Expression of miR-205 was silenced in prostate cancer; since miR-205 transcriptionally activated the expression of tumor suppressors interleukin (IL)-24 and IL-32, miR-205 reintroduction led to the re-expression of IL-24 and IL-32, triggering apoptosis and growth arrest." (PMID 23325049, 2013).
bladder cancer (5 papers, 2020 to 2024). "Meanwhile, it also remains unknown whether IL-32 first induces inflammation and then causes tumor metastasis in bladder cancer, especially by inducing the generation of cancer-associated fibroblasts through inflammation." (PMID 35069212, 2021). "In support of this, the same study found that anti-TIGIT monoclonal antibodies, when used alone, have a dual effect: they boost the antitumor activities of T cells while decreasing IL-32, which in turn inhibits bladder cancer metastasis." (PMID 35656508, 2022). "The failure of the antitumor immune response in bladder cancer was attributed to a subset of TIGIT+ Treg cells overexpressing interleukin IL-32 using single-cell sequencing technology on tissue and experiments in a mouse model." (PMID 35656508, 2022). "To validate the upregulation of IL-32 in bladder cancer tissues, we measured the expression of IL-32 using quantitative real-time PCR (qRT-PCR)." (PMID 35069212, 2021). "To verify the expression of IL-32 in Treg cells in bladder cancer tissues, we analyzed the abundances of IL-32, TIGIT, FOXP3, and CD25 in the TCGA and GTEx as previously reported." (PMID 35069212, 2021). "As expected, we found that administration of α-TIGIT antibody suppressed the expression of IL-32 in bladder cancer tissues 3 days post-injection." (PMID 35069212, 2021). "To explore the specific function of IL-32 in bladder cancer, we incubated bladder cancer cells with a minimal concentration of IL-32 to mimic the effect of the secretion of IL-32 from Treg cells on bladder cancer cells." (PMID 35069212, 2021). "As expected, we noticed that the expression of IL-32 in the bladder cancer cohort was higher than that in the healthy cohort." (PMID 35069212, 2021). "We found that the expression of IL-32 was indeed upregulated in bladder cancer tissues to a certain extent." (PMID 35069212, 2021). "Nevertheless, targeting TIGIT not only reversed immunosuppression by restoring the antitumor immune response mediated by T cells but also suppressed the secretion of IL-32 and inhibited the metastasis of bladder cancer cells." (PMID 35069212, 2021). "To establish an animal model to test the function of targeting TIGIT or IL-32 against bladder cancer, we inoculated C57B6/J mice with MBT-2 cells and analyzed the colocalization of IL-32 and Treg cells." (PMID 35069212, 2021). "Based on single-cell sequencing results, Tregs infiltrating bladder cancer tissues also expressed IL-32." (PMID 35069212, 2021). "To confirm the high expression of IL-32 in bladder cancer, we analyzed data from The Cancer Genome Atlas Program (TCGA) and The Genotype-Tissue Expression Project (GTEx) as previously reported." (PMID 35069212, 2021). "Collectively, our data suggested that IL-32 is highly expressed in Treg cells in bladder cancer tissues." (PMID 35069212, 2021). "The antitumor immune response was suppressed by this subset of Treg cells, while IL-32 promoted bladder cancer metastasis." (PMID 35069212, 2021). "We observed that in both human and mice, the expression of IL-32 was much higher in bladder cancer than in paracancerous tissues." (PMID 35069212, 2021). "We also illustrated the mechanism of the dual effect of targeting TIGIT and revealed the metastasis-promoting effect of IL-32 in bladder cancer." (PMID 35069212, 2021). "To explore the mechanism of the IL-32-mediated invasion and migration of bladder cancer cells, we analyzed the relationship between the abundance of IL-32 and the expression of molecules that mediate the invasion and migration of bladder cancer cells in the TCGA and GTEx databases." (PMID 35069212, 2021). "Furthermore, IL-32 from Treg cells promoted the metastasis of bladder cancer cells, while Treg cells mediated immunosuppression." (PMID 35069212, 2021). "Because IL-32 mediates the metastasis and invasion of bladder cancer cells, targeting TIGIT might inhibit the metastasis of bladder cancer by suppressing the expression of IL-32." (PMID 35069212, 2021).
bladder cancer (continued). "Given the high abundance of IL-32 in Treg cells in bladder cancer tissues, we investigated whether targeting TIGIT with α-TIGIT suppresses the secretion of IL-32." (PMID 35069212, 2021). "Importantly, targeting TIGIT with anti-TIGIT antibodies not only enhanced the antitumor activities of T cells but also suppressed the abundance of IL-32, in turn inhibiting the metastasis of bladder cancer cells." (PMID 35069212, 2021). "Thus, our data indicated that targeting TIGIT inhibited the metastasis of bladder cancer cells by suppressing the expression of IL-32." (PMID 35069212, 2021). "Furthermore, Treg cells expressed IL-32 to promote the migration and invasion of bladder cancer cells." (PMID 35069212, 2021). "Overall, our study revealed the existence of TIGIT+ IL-32+ Treg cells in bladder cancer tissues." (PMID 35069212, 2021). "Hence, as an immune checkpoint, TIGIT not only enhances the antitumor immune response but also inhibits the metastasis of bladder cancer cells by suppressing the expression of IL-32." (PMID 35069212, 2021). "Moreover, IL-32 increased the invasion of bladder cancer cells." (PMID 35069212, 2021). "However, although the expression of IL-32 was positively correlated with Treg cell markers, the relationship between the expression of IL-32 and the prognosis of patients with bladder cancer in clinical practice remains unknown." (PMID 35069212, 2021). "In this study, we identified a specific subset of Treg cells in human bladder cancer tissues that highly expressed TIGIT and IL-32." (PMID 35069212, 2021). "As expected, we noticed that IL-32 was also colocalized with FOXP3 and TIGIT in murine bladder cancer tissues." (PMID 35069212, 2021). "However, whether IL-32 was expressed in Treg cells from bladder cancer tissues remains unknown." (PMID 35069212, 2021). "Although a higher expression of IL-32 has been demonstrated in bladder cancer, its function has not been well characterized." (PMID 35069212, 2021). "We found that IL-32 was colocalized with FOXP3 and TIGIT in clinical bladder cancer samples." (PMID 35069212, 2021). "In our study, we identified the accessory nonimmune function of Treg cells, that is, secreting IL-32 to promote the metastasis of bladder cancer cells." (PMID 35069212, 2021). "Thus, we have provided novel insights into the function of IL-32 in bladder cancer and the effect of anti-TIGIT monoclonal antibodies against bladder cancer." (PMID 35069212, 2021). "However, we observed that IL-32 did not mediate the proliferation of bladder cancer cells." (PMID 35069212, 2021).
colorectal cancer (5 papers, 2015 to 2022). A primary or metastatic malignant neoplasm that affects the colon or rectum. "The TT genotype of rs28372698 has been shown to have significantly reduced IL‐32 levels in colorectal cancer tissue." (PMID 34799941, 2022). "SNP rs28372698 was found in many cancers including thyroid carcinoma and lung, endometrial, ovarian, gastric, bladder, and colorectal cancers that are related to the higher expression of IL-32 resulting in cancer progression." (PMID 35281008, 2022). "Similar to the effect of IL-32 on colorectal cancer, we found that IL-32 enhanced the migration of T24 and EJ cells." (PMID 35069212, 2021). "Our study investigated whether IL-32 expression has clinical significance in the metastases of colorectal cancer (CRC)." (PMID 25889282, 2015). "The overexpression of IL-32 was found to be correlated with metastasis in ESCC and colorectal cancer." (PMID 35281008, 2022).
coronary artery disease (5 papers, 2022 to 2025). "IL-32 enhances the generation of inflammatory proteins and has been linked to coronary artery disease." (PMID 39844544, 2025). "In a Chinese study involving 362 patients with coronary artery disease, IL32 levels correlated with the degree of coronary artery stenosis, suggesting the possibility of a pro-atherogenic activity of IL32 and its association with an unstable plaque-phenotype." (PMID 37108628, 2023). "In line with our data, earlier studies also demonstrated that IL-32 is upregulated in the coronary artery endothelium from individuals with coronary artery disease, and that both IL-32β and γ are the dominantly expressed isoforms in the atherosclerotic arterial vessel wall." (PMID 36992409, 2023). "IL-6 and TNF-α have been directly correlated with obstructive coronary artery disease (CAD) along with IL-32 that was shown to be highly expressed in the coronary artery endothelium in people with CAD." (PMID 36992409, 2023). "Interleukin‐32 (IL‐32) has long been proposed as a biomarker for coronary artery disease (CAD)." (PMID 34799941, 2022). "Recently, IL-36 has aroused great interest because of its dysregulation in inflammatory diseases, in fact the serum levels of IL-36 were found to be significantly higher with coronary artery disease, correlated with TNF-α, IL-6 and IL-32 levels and coronary artery stenosis." (PMID 38961336, 2024).
cutaneous melanoma (5 papers, 2019 to 2023). A primary melanoma arising from atypical melanocytes in the skin. "In view of the previously demonstrated ability of IL-32 to induce potent DC maturation and macrophage activation, we examined the association between IL-32 and myeloid markers in cutaneous melanoma." (PMID 32841222, 2020). "IL32 mRNA expression in cutaneous melanoma was correlated with the infiltration of NK cells and the presence of cytolytic granzyme and perforin, which was associated with a good prognosis in cutaneous melanoma patients." (PMID 37727785, 2023). "Collectively, this study provides the prognostic value of IL32 expression and its potential role as an effective predictive biomarker for NK cell infiltration in cutaneous melanoma." (PMID 34682815, 2021). "GEPIA2 showed that the IL32 mRNA expression levels were significantly elevated in most types of tumors, including cutaneous melanoma (SKCM; skin cutaneous melanoma), as indicated in red." (PMID 34682815, 2021). "The results of this study identified the important role of IL32 in cutaneous melanoma and provided its interaction and function with TILs." (PMID 34682815, 2021). "The IL32 expressions were significantly higher in cutaneous melanoma than in normal tissue, and Kaplan–Meier survival analysis showed a correlation between IL32 expression and good prognosis in cutaneous melanoma patients." (PMID 34682815, 2021). "In conclusion, this study shows that the increased IL32 mRNA expression is significantly related to the infiltration of NK cells in cutaneous melanoma tissues, resulting in a good prognosis in cutaneous melanoma patients." (PMID 34682815, 2021). "Similarly, IL32 has been suggested to show a positive correlation between its expression and the corresponding methylation state in skin cutaneous melanoma." (PMID 37693315, 2023). "In addition, we analyzed the correlation between IL32 expression and the infiltration of natural killer (NK) cells to identify a relevant mechanism between IL32 expression and prognosis in cutaneous melanoma (p = 0.00031)." (PMID 34682815, 2021). "In addition, the correlation between IL32 expression and NK cells, which are effector cells, was analyzed to confirm the impact on cutaneous melanoma survival rate." (PMID 34682815, 2021). "A recent report demonstrated an association between high IL-32 expression and a dedifferentiated phenotype in cell lines, but not in samples from patients with cutaneous melanoma." (PMID 32841222, 2020). "In addition, the correlation between IL32 and various genes of cytolytic molecules, such as GZMA, GZMB, and PRF1, is positive, suggesting that IL32 mRNA expression may increase patient survival through the infiltration and activation of anticancer effector cells in cutaneous melanoma." (PMID 34682815, 2021). "However, the clinical relevance of IL-32 expression in cutaneous melanoma has not been comprehensively studied." (PMID 34682815, 2021).
juvenile idiopathic arthritis (5 papers, 2015 to 2025). Juvenile idiopathic arthritis (JIA) is the term used to describe a group of inflammatory articular disorders of unknown cause that begin before the age of 16 and last over 6 weeks. "SNPs rs10431961(C/T) presence of T allele and rs7188573 (T/C) presence of C allele in the IL32 region were associated with juvenile idiopathic arthritis risk as well as extent of IL32 methylation." (PMID 40977709, 2025). "The rs2239316 of CBP gene is associated with IL32 CpG methylation in CD4+ and CD8+ T cells, which in turn is associated with juvenile idiopathic arthritis." (PMID 38540428, 2024). "Furthermore, CD4+ T cells from patients with juvenile idiopathic arthritis (JIA), the most common autoimmune rheumatic disease of childhood, showed reduction of IL-32 through DNA methylation." (PMID 27182285, 2016).
liver disease (5 papers, 2023 to 2025). "Further research is needed to clarify the underlying mechanisms and the potential impact of IL-32 in liver disease and critical illness." (PMID 40149726, 2025). "Interleukin 32 (IL32) mRNA expression was increased in steatotic liver disease and MASH samples solely in PNPLA3 I148M (rs738409 CG/GG) variant carriers, not in non-carriers (CC)." (PMID 40507973, 2025). "In previous studies, IL-32 was highly upregulated in the liver of individuals with severe liver disease and steatosis due to SLD or hepatitis C virus infection." (PMID 38232700, 2024). "IL-32 is known to be upregulated in the serum of patients with liver disease." (PMID 40149726, 2025). "However, the selection criteria for this cohort differed markedly from previous studies where we found IL32 more strongly associated with the severity of liver damage, as healthy blood donors with metabolic dysfunction were enrolled regardless of liver disease." (PMID 37108628, 2023). "IL-32 did not correlate with albumin levels and the correlation with bilirubin, AST, ALT, and GGT does not necessarily indicate an association of IL-32 with liver disease." (PMID 40149726, 2025).
liver fibrosis (5 papers, 2014 to 2024). "Some studies also have shown that IL-32 is closely associated with liver fibrosis of chronic viral hepatitis." (PMID 25386048, 2014). "Contrary to the findings of our study it was reported that in chronic HCV infection, high levels of IL-32 support hepatic inflammation and liver fibrosis." (PMID 34712431, 2021). "However, we cannot exclude a direct effect of IL32 downregulation on liver fibrosis." (PMID 38232700, 2024). "Elevated IL-32 was then reported in HCV and HBV-infected liver and to correlate with the severity of hepatic inflammation and liver fibrosis." (PMID 24633341, 2014).
osteosarcoma (5 papers, 2016 to 2024). A usually aggressive malignant bone-forming mesenchymal neoplasm, predominantly affecting adolescents and young adults. "IL-32 stimulates the invasion and metastasis of osteosarcoma cells through MMP-13 expression mediated by the AKT pathway." (PMID 38584169, 2024). "Conversely, upregulation of MMP-13 and stimulation of the AKT-pathway mediated by MMP-13 by Interleukin-32 enhances the motility and invasion of osteosarcoma cells, confirming the key role of this metalloproteinase in lung metastases." (PMID 32377334, 2020). "However, IL-32 did not affect MMP-2 and MMP-9 expression in osteosarcoma cells whereas MMP-13 is involved in the IL-32-induced migration, suggesting that different types of proteases affects the migratory processes in a cell-type specific manner." (PMID 27589563, 2016).